SELENOM (selenoprotein M)
Description:
May function as a thiol-disulfide oxidoreductase that participates in disulfide bond formation.
Synonyms: SelM; SEPM
Tractability: Antibody: UniProt predicts a signal peptide or a membrane-spanning region.
Gene: Protein-coding gene on chromosome 22 (31,104,772 to 31,120,069, reverse strand). Ensembl gene ENSG00000198832.
Subcellular location: Cytoplasm, perinuclear region; Endoplasmic reticulum; Golgi apparatus
Subcellular location (Human Protein Atlas): Cytosol; Nucleoplasm
Gene Ontology:
Molecular function: protein binding; oxidoreductase activity
Cellular component: endoplasmic reticulum lumen; endoplasmic reticulum; Golgi apparatus; perinuclear region of cytoplasm
Genetic constraint (gnomAD): Loss-of-function variants: 20 observed, 18.44 expected, observed/expected ratio (o/e) 1.08, 90% interval 0.76 to 1.57. The upper end of that interval is the gene's LOEUF score, 1.57, which puts it in group 6 of 6, group 1 being the genes least tolerant of losing a copy. Missense variants: 230 observed, 201.56 expected, observed/expected ratio (o/e) 1.14, 90% interval 1.02 to 1.27. Synonymous variants: 102 observed, 90.4 expected, observed/expected ratio (o/e) 1.13, 90% interval 0.96 to 1.33.
Homologues: Orthologues: chimpanzee SELENOM (99% identical), macaque SELENOM (99% identical), mouse Selenom (83% identical), rat Selenom (82% identical), dog SELENOM (81% identical), guinea pig SELENOM (79% identical), rabbit SELENOM (77% identical), zebrafish selenom (62% identical), pig SELENOM (50% identical), Caenorhabditis elegans Y76B12C.3 (12% identical), Drosophila melanogaster CG7484 (11% identical). Paralogues in human: SELENOF (13% identical).
Diseases named in the same sentence as SELENOM in open-access papers:
SELENOM is named in the same sentence as 25 diseases in open-access papers, as found by Europe PMC text mining. Sharing a sentence is not in itself a finding about the gene and the disease. The quoted sentences say what the papers report.
hepatocellular carcinoma (5 papers, 2019 to 2023). A malignant tumor that arises from hepatocytes. "Moreover, higher SELENOM expression was discovered in hepatoma cell lines when compared to normal hepatocytes, and its overexpression in HCC liver tissues warranted its proposal as a putative marker for HCC." (PMID 38001759, 2023). "To date, there are few studies on the role of SELENOM in carcinogenesis, with the first data on such regulation were shown with the example of hepatocellular carcinoma (HCC) cells." (PMID 37047442, 2023). "A selenoprotein involved in these mechanisms, SELENOM, has been reported to be upregulated in human hepatocellular carcinoma (HCC) cell lines and liver biopsies of patients with HCV-related cirrhosis." (PMID 31487871, 2019).
Obesity (5 papers, 2016 to 2023). Accumulation of substantial excess body fat. "For example, expression of a couple of selenoproteins, including Gpx1, selenoprotein P and selenoprotein M, is associated with insulin resistance and/or obesity." (PMID 27653523, 2017). "Additionally, selenoprotein M (SelM) was found to support hypothalamic leptin signaling, which may underlie the obesity phenotype observed in SelM KO mice." (PMID 31340540, 2019). "Transgenic mice with targeted deletion of this gene are characterized by obesity, suggesting a possible role of SELENOM in the regulation of body weight and energy metabolism." (PMID 37510406, 2023). "We previously showed that SELENOM knockout mice develop obesity and decreased leptin signaling." (PMID 29385050, 2018).
selenium deficiency (3 papers, 2020 to 2025). A nutritional deficiency disease resulting from inadequate selenium levels in the body, which can lead to impaired function of selenoproteins essential for antioxidant defense and thyroid hormone metabolism. "It is known that SELENOM is expressed in many tissues, but to a greater extent in the brain, is sensitive to selenium deficiency in the brain and can serve as a molecular biomarker of selenium status in this organ, and is involved in the regulation of human neurogenerative diseases." (PMID 37047442, 2023). "Interestingly, several genes encoding selenoproteins (GPX1, GPX4, SELENON, SELENOM, SELENOF, SELENOW, SELENOT) were also downregulated, suggesting molecular evidence of selenium deficiency." (PMID 40459789, 2025).
Alzheimer disease (2 papers, 2013 to 2016). A progressive, neurodegenerative disease characterized by loss of function and death of nerve cells in several areas of the brain leading to loss of cognitive function such as memory and language. "Selenoprotein M (SelM), one of the executants of selenium in vivo, is highly expressed in human brain and most probably involved in antioxidation, neuroprotection, and intracellular calcium regulation, which are the key factors for preventing the onset and progression of Alzheimer’s disease (AD)." (PMID 23439548, 2013).
glioblastoma (2 papers, 2022 to 2023). The most malignant astrocytic tumor (WHO grade IV). "In addition, it was shown that a decrease in SELENOM activity in glioblastoma cells contributed to the functional disorders of the ER, reducing its ability to deposit Ca2+ ions, which led to the emptying of the ER capacity." (PMID 37047442, 2023). "Thus, despite the fact that both selenoproteins SELENOT and SELENOM belong to the same family of membrane proteins with thioredoxin-like folding and are localized in the ER, they have opposite effects on the expression of a number of pro-apoptotic genes in glioblastoma cells." (PMID 35741332, 2022). "In this work, we present for the first time the effects of the suppression of the activity of poorly studied selenoproteins SELENOM and SELENOT in human glioblastoma cells, which is extremely important for understanding the functions of these proteins in brain cells." (PMID 35741332, 2022). "In this work, for the first time, we studied changes in the redox status, calcium homeostasis, and expression of a number of key pro-apoptotic genes and ER stress regulators under conditions of reduced activity of two selenoproteins SELENOM and SELENOT in human glioblastoma cells (A-172)." (PMID 35741332, 2022). "We have shown that a decrease in the expression of SELENOM and SELENOT mRNA in the A-172 human glioblastoma cell line by more than 10 times and the quantitative content of enzymes by more than 3 times leads to ER stress, expressed as a decrease in the ER capacity for storing Ca2+ ions." (PMID 35741332, 2022).
Hepatic steatosis (2 papers, 2024 to 2025). Steatosis is a term used to denote lipid accumulation within hepatocytes. "Our previous studies revealed that Selenoprotein M (SelM) is downregulated in the liver of high-fat diet-fed mice, and its knockdown exacerbates hepatic steatosis, oxidative stress, and fibrosis." (PMID 41150095, 2025).
viral infection (2 papers, 2022 to 2023). "As an antioxidant, selenoprotein M and selenoprotein W-like have been reported that involved in alleviating the oxidative stress and apoptosis caused by virus infection." (PMID 36389847, 2022).
ischemia (1 paper, 2024). A hypoperfusion of the BLOOD through an organ or tissue caused by a PATHOLOGIC CONSTRICTION or obstruction of its BLOOD VESSELS, or an absence of BLOOD CIRCULATION. "Recombinant SELENOM dose-dependently suppressed brain cell necrosis under the excitotoxic effect of glutamate and ischemia-like conditions." (PMID 39200220, 2024). "At the same time, this protective effect is preserved in the glutamate excitotoxicity model, and in the case of ischemia-like conditions, recombinant SELENOM showed the most pronounced protective effect, recorded by gene expression." (PMID 39200220, 2024). "In the ischemia/reoxygenation in vitro model, exogenous recombinant SELENOM also showed high cytoprotective potential." (PMID 39200220, 2024).
nonalcoholic fatty liver disease (1 paper, 2023). "SELENOM overexpression inhibits lipid accumulation and shows a protective effect on nonalcoholic fatty liver disease." (PMID 37895123, 2023).
protein misfolding disease (1 paper, 2024). "In our case series, glutathione peroxidase, selenoprotein P, and selenoprotein M were excreted in urine of cats with renal AA amyloidosis in larger amounts, suggesting a link between oxidative damage and the protein misfolding disease." (PMID 37991136, 2024).
cancer (10 papers, 2019 to 2025). A tumor composed of atypical neoplastic, often pleomorphic cells that invade other tissues. "Selenoprotein M (SelM) is a folded endoplasmicreticulum protein similar to thioredoxin that can regulate the amount of selenium in the diet to prevent cancer and regulate the redox balance of the endoplasmic reticulum." (PMID 40430142, 2025). "This correlation has been observed in cancer in which cell growth is promoted due to high levels of SELENOM and low levels of TXNIP." (PMID 38001759, 2023). "An imbalance of SELENOM can have deleterious effects, but what is more apparent is that SELENOM strikes a balance with its binding partners such as TXNIP; too much can cause increased cell growth and cancers, too little can cause neurodegenerative diseases." (PMID 38001759, 2023). "Indirectly, the involvement of SELENOM in this process was shown by us earlier, since the physiological partners of SELENOM in cancer cells MCF7 and HT-1080 were cytoskeletal actin 1 and 2, which play a key role in cellular processes such as adhesion, migration, polarization, and mitosis." (PMID 34205571, 2021). "Recently, Selenoprotein M (SELM) is upregulated in several types of cancer." (PMID 31274247, 2019). "Although little is known about the specific roles of selenoprotein M, its functional homolog selenoprotein F (SELENOF) has been shown to be involved in cancer progression." (PMID 37741974, 2023). "Since SELENOM is structural homologue of SELENOF, that’s why it may be also involved in the regulation of similar processes in human cancer cell lines; however, this assumption requires further confirmation using other independent approaches." (PMID 37047442, 2023). "Previously, we and other authors have shown that methylselenic acid (MSA), sodium selenite (SS), and selenium nanoparticles (SeNP) can affect the expression of SELENOM and SELENOT mRNA in various cancer and normal cells, depending on the concentration and time of exposure." (PMID 35741332, 2022). "Thus, using the example of five cancer cell lines DU 145, MCF7, A-172, Caco-2, and HT-1080, we studied, firstly, the level of SELENOM mRNA expression increases in proportion to the increase in MSA concentration in all lines." (PMID 34205571, 2021). "In addition, it is known that SELENOM may be involved in the regulation of calcium homeostasis, which has been demonstrated in HT22 and C8-D1A cancer cells." (PMID 37047442, 2023). "Thus, there is a number of strong evidence indicating the involvement of SELENOM in the activation of protective antioxidant mechanisms in brain cells, regardless of whether they are cancer or healthy cells." (PMID 35741332, 2022). "Notably several of these genes are ER-resident selenoproteins (SELENOF, SELENOM, SELENON, SELENOT), thought to be involved in ER-stress response and calcium flux, comprising a potentially important mechanism of selenoprotein-related cancer prevention or promotion." (PMID 31027226, 2019).
infection (5 papers, 2009 to 2025). The state of being infected such as from the introduction of a foreign agent such as serum, vaccine, antigenic substance or organism. "Recently, infection of selenium-deficient Vero E6 cells with SARS-CoV-2 revealed a downregulation of SELENOF, SELENOK, SELENOM, and SELENOS localized in the ER, indicating that infection could adversely affect ER." (PMID 35563199, 2022).
tumor (3 papers, 2014 to 2023). "In some tumor types such as lymphoma, breast, fallopian tube, and ovarian cancers, SELENOM expression is decreased, while in others such as in parotid and uterine tumors, it is increased." (PMID 38001759, 2023). "All six of the tumor cell lines investigated were found to express SELENOM mRNA at a relatively consistent level, while SELENOH and SELENOK levels varied more." (PMID 38001759, 2023).
metabolic disorders (1 paper, 2025). "A recent study shows that promoting the expression of SELENOM protein can alleviate liver damage and metabolic disorders caused by heat stress, which suggests that SELENOM may help organisms adapt to high temperatures through the maintenance of mitochondrial and endoplasmic reticulum homeostasis." (PMID 41378839, 2025).
SELENOM also shares sentences with these, for which no sentence is quoted: renal cell carcinoma (2 papers); Cognitive impairment (1); gastric cancer (1); gastrointestinal disease (1); Insulin resistance (1); kidney disease (1); lymphoma (1); neurodegenerative disease (1); obstructive hydrocephalus (1); steatosis (1); sterility (1).